IBSP (integrin binding sialoprotein)
Description:
Binds tightly to hydroxyapatite. Appears to form an integral part of the mineralized matrix. Probably important to cell-matrix interaction. Promotes adhesion and migration of various cells via the alpha-V/beta-3 integrin receptor (ITGAV:ITGB3).
Synonyms: BSP II; BNSP; BSP; SP-II; BSP-II
Tractability: Antibody: UniProt places it where antibodies can reach, with high confidence; its Gene Ontology location is reachable by antibodies, with high confidence; UniProt predicts a signal peptide or a membrane-spanning region.
Gene: Protein-coding gene on chromosome 4 (87,799,546 to 87,813,329, forward strand). Ensembl gene ENSG00000029559.
Subcellular location: Secreted
Subcellular location (Human Protein Atlas): Vesicles; Cytosol; Nucleoplasm; Predicted to be secreted
Pathways (Reactome):
Extracellular matrix organization: ECM proteoglycans; Integrin cell surface interactions
Gene Ontology:
Molecular function: integrin binding; protein binding; small molecule binding; structural molecule activity
Biological process: osteoblast differentiation; positive regulation of cell adhesion; bone mineralization; cell adhesion; cellular response to growth factor stimulus; extracellular matrix organization; ossification
Cellular component: membrane; extracellular region; non-collagenous component of interstitial matrix; vesicle
Genetic constraint (gnomAD): Loss-of-function variants: 12 observed, 16.85 expected, observed/expected ratio (o/e) 0.71, 90% interval 0.46 to 1.15. The upper end of that interval is the gene's LOEUF score, 1.15, which puts it in group 5 of 6, group 1 being the genes least tolerant of losing a copy. Missense variants: 283 observed, 322.38 expected, observed/expected ratio (o/e) 0.88, 90% interval 0.8 to 0.97. Synonymous variants: 120 observed, 121.33 expected, observed/expected ratio (o/e) 0.99, 90% interval 0.85 to 1.15.
Homologues: Orthologues: chimpanzee IBSP (98% identical), macaque IBSP (95% identical), dog IBSP (80% identical), pig IBSP (78% identical), rabbit IBSP (74% identical), mouse Ibsp (73% identical), guinea pig IBSP (72% identical), rat Ibsp (71% identical).
Diseases named in the same sentence as IBSP in open-access papers:
IBSP is named in the same sentence as 97 diseases in open-access papers, as found by Europe PMC text mining. Sharing a sentence is not in itself a finding about the gene and the disease. The quoted sentences say what the papers report.
breast cancer (65 papers, 2006 to 2026). A primary or metastatic malignant neoplasm involving the breast. "Here, we delved into the associations in between IBSP and breast cancer progression, along with the regulation of IBSP by SMAD4, which was associated with breast cancer metastasis." (PMID 39118232, 2024). "Here, we uncover the important effect and exact underlying mechanism of IBSP in breast cancer metastasis." (PMID 39118232, 2024). "The abnormal expression of the IBSP gene was closely related to bone metastasis, increased malignant risk and the poor prognosis of breast cancer." (PMID 37968615, 2023). "Abnormal expression of the IBSP gene is closely associated with bone metastasis, an increased risk of malignancy and poor prognosis in patients with breast cancer, prostate cancer and non-small-cell lung cancer." (PMID 35646934, 2022). "Increased expression of IBSP (also known as BSP [bone sialoprotein]) was previously reported to be associated with a higher risk of bone metastasis of breast cancer." (PMID 34575612, 2021). "Strikingly, ER+ breast cancer patients with bone metastasis are significantly associated with higher expression of both IBSP and miR-19a." (PMID 34465793, 2021). "The abnormal expression of the IBSP gene is closely related to bone metastasis, increased malignant risk and the poor prognosis of breast cancer, prostate cancer and non-small cell lung cancer." (PMID 31709184, 2019). "IBSP is associated with cancer stem cells, which are thought to be contributors to cancer recurrence, whereas there are insufficient findings to show its specific regulatory mechanisms in breast cancer." (PMID 39118232, 2024). "By using exosomal miR-19a and IBSP to predict the risk of bone metastasis, ER+ breast cancer patients could benefit from this agent in preventing late-onset recurrence in the bone." (PMID 34465793, 2021). "Furthermore, the expression of IBSP is associated with development of metastasis and poor prognosis in breast cancer." (PMID 30918839, 2019). "Beyond secreting miR-19a, ER-positive breast cancer cells also release integrin-binding sialoprotein (IBSP)." (PMID 40564894, 2025). "Our results indicate that IBSP is overexpressed among breast cancer bone metastatic samples and its expression is accompanied by a poorer prognosis." (PMID 39118232, 2024). "There is a need to investigate the mechanisms by which IBSP influences breast cancer progression and its potential as a therapeutic target." (PMID 39118232, 2024). "Our study reveals that IBSP plays a significant role in breast cancer progression through the BMP‐SMAD4 signaling pathway." (PMID 39118232, 2024). "IBSP is highly expressed in a variety of malignant tumors, including breast cancer, prostate cancer, lung cancer, and esophageal squamous cell carcinoma, which is considered to be a promoting factor for tumor migration and invasion." (PMID 38755647, 2024). "Overexpression of IBSP in breast cancer cells led to increased migration and invasion, whereas IBSP interference reduced these behaviors, indicating its role in enhancing tumor progression." (PMID 39118232, 2024). "Breast cancer cells secrete an integrin-binding sialoprotein (IBSP) in bone, which attracts osteoclasts and creates an osteoclast-rich bone microenvironment." (PMID 38464516, 2024). "This study aims to elucidate the role of IBSP in breast cancer, particularly its impact on tumor progression and its relationship with prognosis." (PMID 39118232, 2024). "Bioinformatics analysis from GEPIA2 database indicated that IBSP was clearly elevated in breast cancer tissue samples, and the high expression of IBSP notably reduced general and progress free survival of patients." (PMID 39118232, 2024). "Among 41 cases of ER+ breast cancer patients with metastasis, patients with elevated levels of both IBSP and miRNA-19a showed earlier metastasis within 1000 days." (PMID 38041134, 2023).
breast cancer (continued). "Integrin binding sialoprotein (IBSP) secreted by ER+ breast cancer cells can recruit preosteoclast cells, creating a microenvironment enriched with preosteoclast cells, which facilitates miRNA-19a regulation of bone resorption." (PMID 38041134, 2023). "While IBSP creates an osteoclast-enriched niche, exosomal miR-19a induces osteoclastogenesis, two factors that contribute to creating a favourable site for breast cancer metastasis." (PMID 36612237, 2022). "For instance, EV-embedded miR-19a together with the integrin-binding sialoprotein (IBSP) are secreted by breast cancer cells, and they synergistically influence the bone microenvironment." (PMID 36612237, 2022). "The bone-tropic ER+ breast cancer cells tend to secrete exosomal miR-19a and Integrin-Binding Sialoprotein (IBSP), thus enhancing the expression levels of these markers in circulation of ER+ BC patients." (PMID 35379239, 2022). "More importantly, we clarified a cooperative pathway between IBSP and miR-19a, that mobilizes the bone microenvironment to guide the ER+ breast cancer cells to the bone and support their cell growth." (PMID 34465793, 2021). "Collectively, our study identified exosomal miR-19a and IBSP as mediators of cell–cell communication between breast cancer cells and OC cells, which promotes the vicious cycle of bone metastasis in ER+ breast cancer." (PMID 34465793, 2021). "We found that the expression of exosomal miR-19a and IBSP is significantly upregulated in the secretion of ER+ bone-tropic breast cancer cell lines, as well as in ER+ breast cancer patients with bone metastases." (PMID 34465793, 2021). "This study sheds light on the molecular mechanism of bone metastasis in ER+ breast cancer, which warrants further investigation on the miR19a-IBSP axis for the development of an effective therapeutic strategy." (PMID 34465793, 2021). "Next, we examined the expression of miR-19a and IBSP in breast cancer patients using the TCGA database." (PMID 34465793, 2021). "Because both miR-19a and IBSP are necessary to promote the bone metastasis of ER+ breast cancer cells, we investigated how each of them contributes to the bone-tropic metastasis of cancer cells." (PMID 34465793, 2021). "Bone-derived IBSP plays important roles in breast cancer metastasis through induction of tumor cell seeding into the bone." (PMID 33514011, 2021). "To further clarify the connection between IBSP and bone metastasis of ER+ breast cancer, we performed Kaplan–Meier analyses among 278 breast cancer patients." (PMID 34465793, 2021). "Both exosomal miR-19a and Integrin-Binding Sialoprotein (IBSP) are found to be significantly upregulated and secreted from bone-tropic ER+ breast cancer cells, increasing their levels in the circulation of patients." (PMID 34465793, 2021). "It is reported that IBSP is up-regulated in luminal B2 breast cancer and breast cancer with bone metastasis, while the expression level of IBSP was relatively low in older patients with breast cancer compared with those young patients." (PMID 30918839, 2019). "Identified as a candidate tumor promoter gene, IBSP exhibits frequent overexpression and upregulation in lung cancer, breast cancer, and prostate cancer." (PMID 31709184, 2019). "In addition, integrin-binding sialoprotein (IBSP), a major bone matrix-associated glycoprotein and SMAD-responsive gene, is frequently overexpressed in bone-metastatic breast cancer cells." (PMID 41596432, 2026). "For this purpose, our study screened IBSP as prospective therapeutic candidates in breast cancer." (PMID 39118232, 2024). "Further research into IBSP inhibitors may offer new avenues for improving treatment outcomes and managing breast cancer more effectively." (PMID 39118232, 2024). "Nevertheless, less is known about whether IBSP participates in the progress of BMP‐SMAD mediated breast cancer tumors." (PMID 39118232, 2024).
breast cancer (continued). "Thus, we recognized IBSP to be a promising therapeutic target with highly expressed in breast cancer bone metastasis samples." (PMID 39118232, 2024). "Consequently, our findings implied that SMAD4 promoted the breast cancer migration and invasion through IBSP." (PMID 39118232, 2024). "Furthermore, IBSP exerts an essential function in bone metastasis of estrogen‐positive breast cancer cells." (PMID 39118232, 2024). "Functionally, IBSP in these cells was shown to attract osteoclast cells, facilitating the transfer of exosomal miR-19a and creating a conducive tissue microenvironment for the colonization of breast cancer cells in bone." (PMID 39327610, 2024). "Taken together, our results suggested that IBSP facilitates breast cancer migration and invasion." (PMID 39118232, 2024). "To investigate whether IBSP has a significant effect in breast carcinoma cell bone metastasis, we performed RNA sequencing and found that IBSP expression significantly increased in bone metastasis samples." (PMID 39118232, 2024). "Moreover, IBSP can inhibit osteoblast differentiation and promote the osteolytic metastasis of breast cancer." (PMID 37491214, 2023). "Integrin-binding Sialoprotein (IBSP) secreted by ER+ bone-tropic breast cancer cells could bind to αvβ3 integrin and attract osteoclasts, assisting the delivery of exosomal miR-19a to osteoclast to induce bone metastatic lesions." (PMID 36430471, 2022). "Furthermore, breast cancer cells has been suggested to promote the development of breast cancer bone metastases by releasing exosomes containing miRNA-19a and IBSP." (PMID 36061202, 2022). "A significant upregulation of IBSP protein in the serum of ER+ breast cancer patients with bone metastasis was detected, but not in the serum of patients with only primary breast cancer, advanced ER- breast cancer patients, or ER+ breast cancer patients with visceral metastases other than bone." (PMID 34465793, 2021). "Next, we examined whether the increase of IBSP can be detected in the serum of ER+ breast cancer patients with bone metastases." (PMID 34465793, 2021). "We found that ER+ cancer cells secrete IBSP as a chemoattractant for precursors of OC cells, while exosomal miR-19a enhances the osteoclastogenesis in the early metastatic site, which promotes the bone colonization of ER+ breast cancer cells." (PMID 34465793, 2021). "To test whether both miR-19a and IBSP are required for bone metastasis of ER+ breast cancer cells, we ectopically expressed IBSP and miR-19a in MCF7, and established stable overexpression cell lines." (PMID 34465793, 2021). "Importantly, in both serum and transcriptome profiles of breast cancer patients, we verified that miR-19a and IBSP are correlated with bone metastasis and recurrence status." (PMID 34465793, 2021). "We further investigated whether miR-19a and IBSP are mutually related to bone metastasis of ER+ breast cancer cells." (PMID 34465793, 2021). "IBSP may act differently on different types of breast cancer cells." (PMID 39118232, 2024). "However, the specific role of IBSP in breast cancer remains underexplored." (PMID 39118232, 2024). "Targeting IBSP could be a promising therapeutic strategy for breast cancer treatment." (PMID 39118232, 2024). "While the serum of advanced breast cancer patients in this study was collected during the course of treatment with tumor burden, we did not see a significant difference in the expression of exosomal miR-19a and IBSP between groups with different treatment histories." (PMID 34465793, 2021). "A recent study published in 2021 described that the exosomal transport of miR-19a and integrin-binding sialoprotein (IBSP) might trigger the molecular mechanism of metastasis in osteoclasts and estrogen receptor-positive (ER+) breast cancer and induce the activation of the vicious cycle." (PMID 35011442, 2021).
breast cancer (continued). "It is hoped that our study on the mechanism of IBSP regulation by SMAD4 will create new insights and opportunities for the therapy of breast cancer." (PMID 39118232, 2024). "Among which, IBSP, MMP9, TNFAIP6, DHRS3, RIPK4, and CD200 had a diagnose value for patients with breast cancer bone metastasis." (PMID 30918839, 2019). "In our study, we detected some published potential biomarker of breast cancer bone metastasis, or their function has been reported in breast cancer bone metastasis such as SPARC, IBSP, MMP9, MMP13." (PMID 30918839, 2019). "The elevated expression of IBSP, COL11A1, MYBL2 and UBE2C in breast cancer has previously been reported to directly correlate with tumor progression." (PMID 27359054, 2016). "For exploring whether SMAD4 regulates the aggression and metastasis of breast cancer cells via IBSP, we performed rescue experiments in which cells were co‐transfected with SMAD4 and si‐IBSP." (PMID 39118232, 2024). "There is an increase in IBSP expression in the bone-metastatic group compared to the non-bone-metastatic group among ER+ breast cancer patients, but not among ER− breast cancer patients." (PMID 34465793, 2021). "IBSP was found to be positively correlated with bone metastasis only in ER+ breast cancer patients, but not in ER- breast cancer patients." (PMID 34465793, 2021). "In breast cancer, we observed cancer cell-specific upregulation of IBSP, while the paired normal breast epithelial cells did not express IBSP." (PMID 34465793, 2021). "In contrast, delivery of antimiR-218-5p decreased Wnt activity and the expression of metastasis-related genes, including bone sialoprotein (BSP/IBSP), osteopontin (OPN/SPP1) and CXCR-4, implicating a Wnt/miR-218-5p regulatory network in bone metastatic breast cancer." (PMID 27738322, 2016).
prostate carcinoma (23 papers, 2003 to 2026). A carcinoma that arises from epithelial cells of the prostate gland. "High expression of IBSP is associated with bone metastasis in breast and prostate cancers." (PMID 28678795, 2017). "In this study, the expression of IBSP, a gene highly expressed in castration-resistant prostate cancer clinical specimens specifically metastasizing to bone, was found to be positively regulated by HOXB13/HOXA11-AS." (PMID 33514011, 2021). "We compared the expression levels of eight integrin subunits (ITGA2, ITGA5, ITGAV, ITGB1, ITGB3, ITGB4, ITGB5, and ITGB6), HOXB13, HOXA11-AS, CCL2, CXCL12, and IBSP in prostate cancer tissues that had metastasized to bone, lymph nodes, lungs, liver, and other organs." (PMID 33514011, 2021). "Furthermore, we demonstrated that the HOXB13/HOXA11-AS axis regulated IBSP promoter and integrin subunits specific to prostate cancer bone metastasis." (PMID 33514011, 2021). "Thus, we performed qPCR analysis of IBSP expression in PC3 cells transfected with siRNA targeting HOXB13 or HOXA11-AS to investigate whether HOXB13 and HOXA11-AS regulate IBSP expression in prostate cancer." (PMID 33514011, 2021). "We demonstrated that HOXA11-AS secreted from prostate cancer PC3 cells was able to modify CCL2 and IBSP expression levels in SaOS2 osteoblastic cells in a paracrine manner." (PMID 33514011, 2021). "However, the mechanism by which IBSP is regulated in prostate cancer cells has not yet been elucidated." (PMID 33514011, 2021).
lung cancer (16 papers, 2019 to 2026). A malignant neoplasm involving the lung. "It has been reported that some types of cancers, such as breast, prostate, and lung cancers, have upregulated IBSP expression." (PMID 37501725, 2023). "Several types of cancers, including colon, breast, prostate, and lung cancers were reported to have upregulated IBSP expression." (PMID 34465793, 2021).